Y_RNA (Y RNA )
Gene: Miscellaneous RNA gene on chromosome 12 (44,880,868 to 44,880,969, reverse strand). Ensembl gene ENSG00000201788.
Homologues: Orthologues: chimpanzee Y_RNA (97% identical), macaque Y_RNA (97% identical). Paralogues in human: Y_RNA (90% identical), Y_RNA (88% identical), RNY3 (87% identical), Y_RNA (87% identical), RNY3P1 (86% identical), Y_RNA (86% identical), RNY3P14 (85% identical), Y_RNA (85% identical), Y_RNA (84% identical), RNY3P11 (83% identical), RNY3P3 (83% identical), RNY3P5 (83% identical), and 95 more.